NAMPT (nicotinamide phosphoribosyltransferase)
Diseases named in the same sentence as NAMPT in open-access papers (continued):
Sharing a sentence is not in itself a finding about the gene and the disease.
Hypertension (9 papers, 2018 to 2025). The presence of chronic increased pressure in the systemic arterial system. "Thus, we hypothesize that decreased NAMPT expression is associated with hypertension and may serve as a biomarker of hypertension." (PMID 33488923, 2020). "In contrast, NAMPT overexpression exhibits a protective effect against Ang II-induced hypertension by suppressing the production of ROS." (PMID 39273473, 2024). "Animal experiments confirmed reduced RASD1 and NAMPT expression in hypertrophic hearts from female SHRs with spontaneous hypertension." (PMID 39535387, 2024). "Immunochemical staining and Western blotting revealed a slight decrease in NAMPT levels in patients with hypertension." (PMID 33488923, 2020). "In the present study, we identified NAMPT as a crucial regulator of hypertension, because the expression of NAMPT was significantly downregulated in both patients with hypertension and experimental animals." (PMID 33488923, 2020). "In the present study, the expression of NAMPT was significantly downregulated in both patients with hypertension and experimental animals." (PMID 33488923, 2020). "In vivo, overexpression of NAMPT protected against angiotensin II- (Ang II-) induced hypertension by inhibiting ROS production via sirtuin 1 in mouse aortic endothelial cells (MAECs) and mouse aortic vascular smooth muscle cells (MOVAs)." (PMID 33488923, 2020). "Collectively, this study is the first to show that NAMPT prevents Ang II-induced hypertension by inhibiting excess ROS accumulation, at least in part through the regulation of SIRT1 expression and the NAD concentration." (PMID 33488923, 2020). "Based on our results, the expression of NAMPT was significantly downregulated in both patients with hypertension and experimental animals." (PMID 33488923, 2020). "In the present study, we identified NAMPT as a crucial regulator of hypertension, because NAMPT expression was significantly downregulated in both patients with hypertension and experimental animals." (PMID 33488923, 2020). "Based on these results, NAMPT haplodeficiency significantly exacerbates Ang II-induced hypertension." (PMID 33488923, 2020). "We generated NAMPT haplodeficient (NAMPT+/-) mice to determine the effects of NAMPT on Ang II-induced hypertension." (PMID 33488923, 2020). "Nevertheless, gestational hypertensive patients carrying the rs3801266 “AG” and “GG” genotypes had higher visfatin/NAMPT levels compared to gestational hypertensive patients carrying the “AA” genotype." (PMID 30618791, 2018). "NAMPT haplodeficiency exacerbates Ang‐II‐induced hypertension." (PMID 41021357, 2025). "Furthermore, NAMPT expression was reduced in the aortic wall tissues of patients with hypertension and rats with angiotensin II (Ang‐II)‐induced hypertension, accompanied by aortic wall fibrosis." (PMID 41021357, 2025). "Overall, NAMPT may be an innovative marker and therapeutic target for the intervention of hypertension and related vascular diseases." (PMID 33488923, 2020). "Our study revealed a critical role for NAMPT in regulating Ang II-induced hypertension." (PMID 33488923, 2020). "In conclusion, NAMPT might be a novel biomarker and a therapeutic target in hypertension." (PMID 33488923, 2020). "However, the molecular mechanism of NAMPT and its function in hypertension are not well understood." (PMID 33488923, 2020). "However, up to date, the molecular mechanism of NAMPT and its function in hypertension associated with oxidative stress have not been well studied." (PMID 33488923, 2020). "NAMPT, a rate-limiting enzyme in NAD+ biosynthesis, is significantly downregulated in both patients and experimental animals with hypertension." (PMID 39273473, 2024). "The overexpression of NAMPT partially inhibits Ang II-induced elevated ROS levels by regulating SIRT1 and the concentration of NAD+, thus relieving Ang II-induced hypertension." (PMID 36632457, 2023).
Hypertension (continued). "After 12 weeks of EOJ consumption, four genes related to hypertension (PTX3, NLRP3, NPSR1 and NAMPT) were differentially expressed in peripheral blood mononuclear cells (P < 0.05)." (PMID 32661681, 2021). "Because NAMPT mainly regulates the SIRT family in the cardiovascular system, we used qRT-PCR to examine SIRT1-7 expression in MAECs and MOVAs transfected with the NAMPT plasmid and stimulated with Ang II to determine which SIRTs play the most important role in the development of hypertension." (PMID 33488923, 2020). "However, the function and regulation of NAMPT in hypertension have not been extensively explored." (PMID 33488923, 2020).
metabolic syndrome (9 papers, 2010 to 2025). A cluster of metabolic risk factors for CARDIOVASCULAR DISEASES and TYPE 2 DIABETES MELLITUS. "In contrast, hepatocyte SIRT1 was dispensable for NAMPT to produce therapeutic effects on light-cycle thermogenesis, dyslipidemia, and hepatic de novo lipogenesis." (PMID 35228549, 2022). "In obese and overweight patients with metabolic syndrome, the expression of NAMPT increases in the plasma and simulates the effect of insulin." (PMID 30755828, 2019). "Oxidative stress is reported to depress NAMPT-mediated NAD+ biosynthesis during metabolic syndrome and aging." (PMID 28786950, 2017). "Of interest we observed that circulating visfatin/NAMPT levels were increased in elderly women with components of metabolic syndrome and decreased with age; however, the difference between subjects with and without metabolic syndrome was small." (PMID 27293305, 2016). "In contrast, NAMPT and SIRT1 exerted independent effects on diet-induced dyslipidemia." (PMID 35228549, 2022).
Arthritis (8 papers, 2008 to 2025). Inflammation of a joint. "Previously, we found that MAN can effectively alleviate experimental arthritis in rats, and inhibit nicotinamide phosphoribosyltransferase (NAMPT) signaling activation in immune cells." (PMID 34305602, 2021). "The purpose of this study was to investigate NAMPT’s role in arthritis using mouse and cellular models." (PMID 30774990, 2019). "The beneficial properties of FK866 observed herein would be in accord with recent reports indicating that NAMPT inhibitors can ameliorate animal model symptomatology of inflammatory diseases such as arthritis, endotoxic shock and autoimmune encephalitis." (PMID 22490786, 2012). "NAMPT inhibitors have proven beneficial in inflammatory animal models of arthritis and endotoxic shock as well as in autoimmune encephalitis." (PMID 22490786, 2012). "In RA, expression of NAMPT is upregulated in the inflamed synovial tissue of mice with antigen-induced arthritis, and in plasma and synovial fluid from RA patients." (PMID 18493620, 2008). "Interestingly, the pharmacological inhibition of visfatin/NAMPT by Apo866, a specific inhibitor of NAMPT activity, prevents arthritis progression." (PMID 24438745, 2014). "Importantly, a specific competitive inhibitor of NAMPT effectively reduced arthritis severity with comparable activity to etanercept, and decreased pro-inflammatory cytokine secretion in affected joints." (PMID 18493620, 2008). "In this context, cell lysis could be responsible for the release of NAMPT in the extracellular compartment thus accounting for the increased NAMPT concentration found in the serum and tissues of RA patients and in mouse arthritis models (and our results)." (PMID 18493620, 2008). "In this context, the abnormally elevated NAMPT levels reported in human and experimental arthritis (, and our results on CIA) could well result from the hypoxic conditions in the rheumatoid synovial microenvironment further contributing to the angiogenic process found in RA." (PMID 18493620, 2008).
Ewing sarcoma (8 papers, 2017 to 2025). A small round cell tumor that lacks morphologic, immunohistochemical, and electron microscopic evidence of neuroectodermal differentiation. "Taken together, our data reveal evidence of an important role of the NAMPT-mediated NAD salvage pathway in the energy homeostasis of EwS cells and suggest NAMPT inhibition as a potential new treatment approach for Ewing sarcoma." (PMID 28160567, 2017). "In this study, we evaluated the efficacy and mechanisms of action of OT-82, a novel, high-potency NAMPT inhibitor with a favorable toxicity profile, in preclinical models of Ewing sarcoma (EWS), an aggressive pediatric malignancy with previously reported selective sensitivity to NAMPT inhibition." (PMID 32908120, 2020). "Although it is not BRCA-deficient, Ewing sarcoma is also characterized by defective HR, further supporting the idea that cancers with defective DNA repair mechanisms may have increased susceptibility to NAMPT inhibition." (PMID 32010616, 2019). "Indeed, a potentiating effect was shown between NAMPT inhibitors and the PARP inhibitors olaparib or niraparib in triple-negative breast cancer and Ewing sarcoma." (PMID 34068917, 2021). "In Ewing sarcoma and some NSCLC models, cells were able to maintain ROS balance in the presence of a NAMPT inhibitor, suggesting that there may be cell-type dependent differences in these effects." (PMID 32010616, 2019).
heart failure (8 papers, 2016 to 2026). Inability of the heart to pump blood at an adequate rate to meet tissue metabolic requirements. "NAD+ precursors such as nicotinamide riboside (NR) and nicotinamide mononucleotide (NMN), which can bypass NAMPT, are protective in preclinical models of heart failure." (PMID 39171530, 2024). "In fact, increasing levels of NAD+ have been shown to improve many forms of heart failure, and cardiac-specific overexpression of NAMPT in transgenic mice has been shown to reduce infarct size and promote cardiomyocyte survival by preventing the decrease in NAMPT and increasing NAD+ content post-MI." (PMID 40695797, 2025). "Thus, it has been suggested that activation of NAD+ synthesis via the NRK2 pathway represents a common adaptive mechanism in heart failure, while the Nrk2 gene may be activated in response to NAMPT inhibition." (PMID 34684434, 2021). "This route is important in NAMPT-expressing cells, where NAMPT expression declines under metabolic stress, and in nervous tissues, where NRK2 is induced by axonal injury and heart failure." (PMID 41516357, 2026). "NAD+ concentration is decreased in failing human hearts, and expression of nicotinamide phosphoribosyltransferase (NAMPT), the rate-limiting enzyme for NAD+ synthesis, is downregulated during heart failure and in myocardial ischemic injury." (PMID 39171530, 2024). "Conversely, downregulation of Sirt1 is observed in cardiomyocytes from patients with advanced heart failure; indeed, the whole AMPK/Sirt1/NAMPT axis appears to be downregulated in the aging/failing heart." (PMID 36139463, 2022). "Furthermore, a transition from fatty acid oxidation and oxidative phosphorylation to other forms of substrate metabolism (glycolysis and oxidation of ketones) often occurs with the development of heart failure and cardiomyopathy; while the NAD+/NADH ratio decreases, the NAMPT enzyme is repressed." (PMID 34684434, 2021).
myocardial infarction (8 papers, 2012 to 2026). Gross necrosis of the myocardium, as a result of interruption of the blood supply to the area, as in coronary thrombosis. "The potential biomarker of AMI, CDR1as, promotes arrhythmia in myocardial infarction by directly targeting the NAMPT and causing mitochondrial dysfunction in AMI." (PMID 41538664, 2026). "We detected the delivery efficiency of adenovirus harboring NAMPT in the myocardium and found that NAMPT reduced I/R-induced myocardial infarction, as revealed by Evans blue-TTC staining." (PMID 37370086, 2023).
steatosis (8 papers, 2015 to 2024). Increased lipid within the cytoplasm of cells. "Previous studies have demonstrated the regulatory role of NAMPT in NAFLD, and upregulating NAMPT through various strategies has been shown to prevent steatosis and inflammation." (PMID 38601640, 2024). "Elevation of TG levels byNAMPT knockdown was notably reversed by additionof NAD, confirming the effect of NAMPT inhibition onhepatic steatosis." (PMID 32779442, 2020). "Human studies investigated how plasma and liver NAMPT protein levels are affected in subjects with steatosis and NAFLD." (PMID 31510030, 2019). "Other studies suggest that manipulation of NAMPT renders the liver more susceptible toward hepatic lipid accumulation, as both treatment with the NAMPT inhibitor FK866 and overexpression of a dominant-negative Nampt mutation induces susceptibility to steatosis development." (PMID 34762911, 2021). "NAMPT, PHLDA1, RALGDS, GADD45B, and FOSL2 were all in the brown module, with a lower expression for steatosis and NASH samples and with a higher expression for normal samples." (PMID 34041361, 2021). "In contrast, SIRT1-independent, NAMPT-upregulated processes included neutrophil chemotaxis and complement pathway concepts, whereas NAMPT suppressed de novo lipogenesis, hepatic steatosis, adipogenesis and retinoic acid pathways independent of SIRT1." (PMID 35228549, 2022).
thyroid cancer (8 papers, 2014 to 2025). "Previously, in thyroid cancer patients, we observed the overexpression of NAMPT in tissue samples, which was related to more advanced tumor stages with metastases to the lymph nodes." (PMID 36233428, 2022). "We have previously found that NAMPT expression correlated with thyroid cancer stage and lymph node invasion." (PMID 29546048, 2018). "In a previous study, we also observed that NAMPT expression in thyroid cancers is positively correlated with advanced tumor stage and lymph node involvement." (PMID 29546048, 2018). "We found NAMPT overexpression in thyroid glands of patients with Graves' orbitopathy and thyroid cancers." (PMID 29546048, 2018). "We have shown that NAMPT overexpression in patients with Graves' orbitopathy and thyroid cancers was at a similar level." (PMID 29546048, 2018). "In view of these results, we aimed to analyze NAMPT expression in thyroid tissue derived from patients with Graves' disease with and without orbitopathy, patients with toxic nodular goiters and thyroid cancers, and healthy controls." (PMID 29546048, 2018). "NAMPT has also antiapoptotic properties, and its overexpression was observed in many cancers, including thyroid cancers." (PMID 29546048, 2018). "NAMPT expression was significantly higher in thyroid cancers (P < 0.0001), and it was positively correlated with tumor stage (P = 0.0012; r = 0.493)." (PMID 25946974, 2015). "Due to limited sample size, our study was underpowered to investigate the differences in NAMPT expression between certain histopathological types of thyroid cancer and this should be addressed in further studies." (PMID 25946974, 2015). "NAMPT expression in thyroid cancers was positively correlated with tumor stage (P = 0.0012; r = 0.493), and it was significantly higher in tumors staged pT3 or pT4 (16 cases) than in tumors staged pT1 or pT2 (24 cases) (P = 0.0106)." (PMID 25946974, 2015). "Further studies are needed to explain the role of NAMPT in thyroid cancer biology and the possible use of NAMPT inhibitors in thyroid cancer." (PMID 25946974, 2015). "NAMPT expression in thyroid cancers significantly correlated with survivin and with survivin splice variant DEx3 expressions (P < 0.0001; r = 0.624 and P = 0.0239; r = 0.357, respectively)." (PMID 25946974, 2015). "Further studies are needed to explain the role of NAMPT in thyroid cancer biology and to investigate the possible use of NAMPT inhibitors in thyroid malignancies." (PMID 25946974, 2015). "We found that NAMPT expression is significantly higher in thyroid cancers and it is correlated with tumor stage." (PMID 25946974, 2015). "Lack of correlation between NAMPT and survivin expressions neither in benign lesions nor in healthy tissues observed in our study further confirms different regulatory patterns of expression of both NAMPT and survivin in thyroid cancers." (PMID 25946974, 2015). "NAMPT expression was found in all analyzed tissue samples, and it was significantly higher in thyroid cancers than in the control group (P < 0.0001)." (PMID 25946974, 2015). "Interestingly, we found significant NAMPT overexpression in the thyroid glands of patients with GO, as well as in thyroid cancers." (PMID 29546048, 2018). "However, relative NAMPT expression in toxic nodular goiters was still lower than that in thyroid glands derived from patients with Graves' orbitopathy and thyroid cancers." (PMID 29546048, 2018). "The strong correlation between NAMPT and survivin expression in thyroid malignancies shown in our study also supports the hypothesis that high NAMPT expression might be a prognosis predictor for thyroid cancer." (PMID 25946974, 2015). "Despite the fact that there are no data reporting that Graves' patients who have eye changes are at higher risk of thyroid cancers, we could speculate that, in the latter group of patients, NAMPT/visfatin/PBEF could be also partially responsible for worse prognosis of thyroid cancers." (PMID 29546048, 2018).
thyroid cancer (continued). "Our aim was to analyze NAMPT expression in thyroid tissue derived from patients with Graves' disease with (GD) and without (GO) orbitopathy, patients with toxic nodular goiters (TNG) and thyroid cancers (TC), and healthy controls." (PMID 29546048, 2018).
COVID-19 (7 papers, 2020 to 2024). A disease caused by infection with severe acute respiratory syndrome coronavirus 2. "In regard to cytokines and chemokine expression between COVID-19 cases we found that the highest avg (log2) values showing fold change were indicated by CCL5, IL1R2, NAMPT and PPBP." (PMID 34824360, 2021). "The highly correlated expression of RGS2 with CXCL8, PTGS2, NAMPT, ILB1 and further inflammatory genes in COVID-19 positive nasopharyngeal swabs suggests the involvement of a common regulator, which might explain the distinct classes of COVID-19 symptoms." (PMID 36143181, 2022). "Interestingly, treatment of monocytes with the STAT-inhibitor and COVID-19 drug Ruxolitinib not only reduced the expression of STAT-targets CXCR4 and NAMPT, but also increased the expression of proinflammatory markers CXCL8 and CXCL2." (PMID 35998224, 2022).
endometrial cancer (7 papers, 2015 to 2024). Primary or metastatic malignant neoplasm involving the endometrium (mucous membrane that lines the endometrial cavity). "In endometrial cancer, NAMPT expression is shown to be relatively higher in endometrial carcinoma patient tissues when compared to normal tissues and that high NAMPT levels lead to poor survival outcomes." (PMID 39272943, 2024). "In endometrial cancer, NAMPT was found to promote the cell proliferation in both KLE and Ishikawa cells through the G1/S phase progression triggering by MAPK-ERK1/2 and PI3K-Akt signaling axis activation." (PMID 35565188, 2022). "In contrast, lower NAMPT levels were observed in thyroid cancer, testis cancer, endometrial cancer, and ovarian cancer." (PMID 35565188, 2022). "NAMPT immunohistochemical expression was found to be increased in endometrial cancer and further increased in a subgroup with advanced tumor stage." (PMID 25946974, 2015). "Additionally, eNAMPT levels were found to be elevated in the serum from endometrial cancer patients, and this was found to be correlated with NAMPT expression in the tumor tissue." (PMID 39272943, 2024). "Among 52 proteins previously identified by the research team, 8 proteins (MMP9, KPYM, LDHA, CADH1, NAMPT, MPO, ENOA and CAPG) achieved the highest accuracy in diagnosing endometrial cancer in CVF." (PMID 39194522, 2024). "This study identified 28 differentially expressed proteins in endometrial cancer samples, with LDHA, PKM, MMP9, NAMPT, and SPIT1 showing the best performance in distinguishing endometrial cancer from normal tissues." (PMID 39194522, 2024). "Additionally, NAMPT, ENOA, CATD, and GSTP1 were differentially found between endometrial cancer and control samples, enabling the distinction of hyperplasia cases." (PMID 39194522, 2024).